FOXC1 (forkhead box C1)
Diseases named in the same sentence as FOXC1 in open-access papers (continued):
Sharing a sentence is not in itself a finding about the gene and the disease.
gastric cancer (23 papers, 2016 to 2025). A primary or metastatic malignant neoplasm involving the stomach. "In gastric cancer, FOXC1 promotes cell proliferation by enhancing GPX8 transcription to activate Wnt signaling pathway." (PMID 39093497, 2024). "A previous study in gastric cancer confirmed that FOXC1 binds to the promoter region of the β-catenin gene and transactivates its expression, which activates WNT signaling." (PMID 39430239, 2024). "FOXC1 can also promote the proliferation of gastric cancer cells by activating the Wnt signaling pathway." (PMID 35096062, 2022). "The MTT, colony formation, flow cytometry, wound healing, transwell, and western blotting were performed to examine the function of miRNA-149 and FOXC1 in the development of gastric cancer." (PMID 34957298, 2021). "Silencing FOXC1 significantly inhibits the growth and migration of gastric cancer AGS and MKN28 cells, promotes apoptosis thereof, and blocks the cell cycle in the G1 phase." (PMID 34957298, 2021). "To further investigate the function of FOXC1 in gastric cancer cells, we used RNA interference technology to silence the expression of FOXC1 in AGS and MKN28 cells." (PMID 34957298, 2021). "Additional independent validation studies performed with greater statistical rigor are therefore required to ascertain the true prognostic value of FOXC1 expression in the case of both esophageal as well as gastric cancer." (PMID 34540690, 2021). "LincRNA MCM3AP−AS1 induced upregulation of FOXC1 expression, indicating cisplatin resistance in gastric cancer patients." (PMID 34540690, 2021). "What is more, FOXC1 was highly expressed in gastric cancer tissues and cells; the silencing of FOXC1 inhibited the biological function of AGS and MKN28 cells." (PMID 34957298, 2021). "qRT-PCR was used to detect the expression of miRNA-149 and FOXC1 in gastric cancer tissues and cells." (PMID 34957298, 2021). "Results from immunohistochemistry and qRT-PCR showed that FOXC1 was highly expressed in gastric cancer tissues." (PMID 34957298, 2021). "FOXC1 expression status has now also been shown to be a poor prognostic indicator in multiple gastrointestinal cancers including esophageal cancer, gastric cancer, liver cancer, pancreatic cancer and colon cancer." (PMID 34540690, 2021). "Annexin V and PI double staining revealed that compared to the control group, silencing FOXC1 induced apoptosis of gastric cancer cells." (PMID 34957298, 2021). "Analysis of the expression of FOXC1 in gastric cancer tissues using TCGA database showed that it was highly expressed in 414 gastric cancer tissues compared to that in 36 adjacent tissues." (PMID 34957298, 2021). "In this study, we investigated the inhibitory effects of miR-149 on the biological functions of gastric cancer cells by targeting FOXC1." (PMID 34957298, 2021). "Silencing FOXC1 was consistent with overexpression of miR-149 on the proliferation, cycle, apoptosis, and migration of gastric cancer cells, which suggest that FOXC1 mediates the regulation of miR-149 in gastric cancer progression." (PMID 34957298, 2021). "miRNA-149 inhibits the biological behavior of gastric cancer by targeting FOXC1, providing a promising target in the treatment of human gastric cancer." (PMID 34957298, 2021). "Samples (n = 120) were evaluated from the tumors of patients with gastric cancer; 34 samples were from stage T1-T2, 86 were from stage T3-T4, and the proportion of FOXC1 positive tumors in each group was 55.8% (19/34) and 76.7% (66/86), respectively." (PMID 30564302, 2018). "Similarly, two independent studies in gastric cancer thus far have provided preliminary confirmation of the prognostic significance of FOXC1 expression with regard to overall survival." (PMID 34540690, 2021). "The mRNA levels of FOXC1 suggested that it is highly expressed in gastric cancer cells." (PMID 34957298, 2021). "This study is done to investigate whether FOXC1 as a target gene of miR-149 mediates its inhibitory effect on gastric cancer cells." (PMID 34957298, 2021).
gastric cancer (continued). "To further investigate the mechanism of miR-149 in regulating the biological behavior of gastric cancer cells, we predicted that miR-149 had binding sites with FOXC1 3′-UTR through the TargetScan database and constructed FOXC1 wild-type and mutant 3′-UTR luciferase vectors." (PMID 34957298, 2021). "The aim of this study was to investigate the function of miRNA-149 and FOXC1 in gastric cancer." (PMID 34957298, 2021). "Studies have shown that miR-149 plays an important role in many cancers, although its regulatory role in the FOXC1-mediated progression of gastric cancer remains unclear." (PMID 34957298, 2021). "The expression of FOXC1 has significance in the development, progression, and metastasis of gastric cancer, and overexpression of FOXC1 may serve as a useful marker for predicting the outcome of patients with gastric cancer." (PMID 27403158, 2016). "Additionally, we elucidated the effect of FOXC1 on the function of gastric cancer cells." (PMID 34957298, 2021). "However, the ability of miR-149 to regulate the biological functions of gastric cancer cells by targeting FOXC1 remains unclear." (PMID 34957298, 2021). "Once in the nucleus, FOXC1 separates from β-catenin, thereby regulating c-MYC transcription and promoting gastric cancer cell proliferation." (PMID 39430239, 2024). "miR-138-5p targets FOXC1 and DEK to inhibit the progression of prostate cancer and proliferation of gastric cancer, respectively." (PMID 36005825, 2022). "FoxC1-induced transcriptional activation of GPX8 activates Wnt signaling and subsequent gastric cancer cell proliferation." (PMID 35456975, 2022). "Further, FOXC1 negatively regulates DKK1 (a WNT inhibitor) expression by binding to its promoter region, thereby activating Wnt pathway in gastric cancer cells." (PMID 34540690, 2021). "Human gastric cancer cell lines AGS and MKN28 were cultured and transfected with miR-149 overexpression plasmid and its control or FOXC1 siRNA and its control." (PMID 34957298, 2021). "Our results showed that FOXC1 and FOXD1 were upregulated in gastric cancer compared with normal tissues, which provides additional evidence for their roles of potential biomarkers." (PMID 27403158, 2016). "Moreover, expression of FOXC1 has been shown to be regulated by MCM3AP-AS1 in oral squamous cell carcinoma and gastric cancer through modulation of expressions of miR-204-5p and miR-138, respectively." (PMID 35790972, 2022). "The expression of FOXC1 was upregulated in gastric cancer tissues and cell lines compared to that in control nontumor tissues and normal gastric epithelial cell lines, which was consistent with our prediction from TCGA database." (PMID 34957298, 2021). "miR-149 is low expressed in gastric cancer cells and inhibits the proliferation and metastasis of gastric cancer AGS and MKN28 cells by targeting FOXC1, which may be a potential new target for GC therapy." (PMID 34957298, 2021). "mRNA and protein expression of FOXC1 in gastric cancer (GC) tissues were dramatically higher than those in adjacent normal tissues." (PMID 29552326, 2018). "qPCR and western blot were applied to evaluate mRNA and protein levels of FOXC1 in non-malignant (GES-1) and gastric cancer cell lines (AGS, SGC-7901, MGC-803, MKN-45, HGC-27)." (PMID 33987183, 2021).
aniridia (20 papers, 2011 to 2025). Aniridia is a congenital ocular malformation characterized by the complete or partial absence of the iris. "The remaining 3 of 22 families have deletions encompassing FOXC1 (a known cause of atypical aniridia)." (PMID 38050128, 2024). "Later, FOXC1 mutations were discovered in patients with aniridia, Peters anomaly and primary congenital glaucoma (PCG)." (PMID 36284357, 2022). "Mutations in the PAX6, PITX2, and FOXC1 genes have been associated with aniridia and ARS in an autosomal dominant manner." (PMID 27463523, 2016). "In addition to PAX6, aniridia-like phenotypes have been observed in patients with rare variants in FOXC1 and PITX2 as well." (PMID 39449022, 2024). "Previously, only one variant in FOXC1 (c.454T>G; p.Trp152Gly) has been associated with aniridia." (PMID 35327965, 2022). "Of these nine aniridia cases, seven had known congenital glaucoma (one unknown), many presenting as infants with buphthalmos, suggesting that this is more common in FOXC1- than PAX6-associated aniridia." (PMID 30242502, 2019). "Rarely, aniridia cases are associated with FOXC1, PITX2 and/or their regulatory regions." (PMID 30242502, 2019). "Another FOXC1 mutation (p.Met161Lys) has been reported to cause both aniridia and ARS." (PMID 27463523, 2016). "Rarely, isolated aniridia is caused by mutations in FOXC1 or PITX2." (PMID 27124303, 2016). "One can speculate that either the homozygous 11q24.2 deletion alone or in concert with the homozygous FOXC1 missense variant was associated with the classic aniridia phenotype." (PMID 21423868, 2011). "In addition, FOXC1 is another key gene associated with congenital aniridia." (PMID 39449022, 2024). "Furthermore, FOXC1 is an important gene associated with congenital aniridia." (PMID 39449022, 2024). "A SNV in exon 1 of the FOXC1 gene in two related patients (A44, mother–A45, daughter) displaying aniridia." (PMID 38459225, 2024). "We postulate that FOXC1-related aniridia appears to be the extreme end of iris hypoplasia rather than true aplasia as is seen in PAX6-related aniridia." (PMID 35327965, 2022). "Here, we describe a novel truncating variant in FOXC1 causing autosomal dominant atypical ASD with highly variable phenotypic spectrum including variable iris hypoplasia and aniridia in a large Caucasian family." (PMID 35327965, 2022). "Up to 90% of cases with aniridia can be explained by loss‐of‐function mutations in the PAX6 gene; rarely, disruption of FOXC1, PITX2, and other genes have been identified as causative." (PMID 33973683, 2021). "Mutations in the PAX6, PITX2, and FOXC1 genes have been associated with ARS and aniridia in an autosomal-dominant manner." (PMID 31341655, 2019). "Of note, 3 of the 4 individuals reported here with FOXC1 haploinsufficiency, and the individual with the PITX2 cis-regulatory mutation have congenital glaucoma associated with their aniridia phenotype." (PMID 27124303, 2016). "Because of the mixed anterior segment anomalies between the two eyes of this patient and the association of Wilm’s tumor in sporadic cases of aniridia, genetic testing was conducted for PITX2, FOXC1, and PAX6." (PMID 21617748, 2011). "It is known that mutations in the transcription factor PITX2 and FOXC1 genes lead to ARS, while mutations of the PAX6 gene underlies many cases of aniridia." (PMID 21617748, 2011). "This possibility is supported by recent reports: 1) mutations in the forkhead box C1 gene (FOXC1, OMIM 601090) are associated with aniridia in two families and 2) aniridia in patients with preserved visual function are not related to PAX6 mutations." (PMID 21850189, 2011). "Axenfeld–Rieger syndrome and primary congenital glaucoma share some causative genes (FOXC1 and CYP1B1) that may also induce other subtypes of ASD (aniridia, iris hypoplasia, and Peters anomaly), while the LTBP2 gene is confined to primary congenital glaucoma." (PMID 40364033, 2025).
aniridia (continued). "Surprisingly, aniridia was not reported to be associated with FOXC1 in any of the reviewed publications and to the best of our knowledge is a unique feature of the SNP associated with the FOXC1-affected family reported in this study." (PMID 35327965, 2022). "It is also possible that there are mutations in other genes which contribute to aniridia given that mutations in FOXC1 are associated with aniridia and that no PAX6 mutations were detected in aniridia patients with preserved visual function." (PMID 21850189, 2011). "In addition, cases of ARS have been described associated with a deletion of PAX6, and cases of bilateral aniridia with proven PITX2 and FOXC1 mutations." (PMID 21617748, 2011). "Although no genetic or genomic cause for classic aniridia was found in one (Patient 7), in the other (Patient 9) there was a homozygous FOXC1 missense variant previously reported as responsible for anterior segment dysgenesis in the heterozygous state." (PMID 21423868, 2011). "Furthermore, FOXC1 and PITX2 variants were also associated to aniridia-like phenotypes." (PMID 34610801, 2021). "Furthermore, few studies have found that FOXC1 and PITX2 gene mutations can also lead to aniridia." (PMID 30621664, 2019). "However, this case has to be viewed in the context of the FOXC1 mutation and lack of other siblings in whom we can verify the segregation pattern of this deletion with respect to the classic aniridia phenotype." (PMID 21423868, 2011). "Other genes, including FOXC1, CYP1B1, PITX2 and FOXE3, have been identified as potential contributors to iris hypoplasia and aniridia-like phenotypes." (PMID 39449022, 2024). "The most common cause of aniridia is pathogenic variants in the PAX6 gene, accounting for up to 90% of cases, with FOXC1, PITX2, and a few other genes explaining some of the remaining cases but still leaving about 5%–10% of aniridia genetically unexplained." (PMID 33973683, 2021). "Although there have been reports of lack of visible iris in patients with heterozygous FOXC1 as well as heterozygous PITX2 mutations, these previously-reported patients would not be considered classic aniridia as they did not have documented keratopathy, lens opacity, or foveal hypoplasia." (PMID 21423868, 2011).
congenital glaucoma (20 papers, 2010 to 2025). "In the context of Axenfeld–Rieger syndrome, FOXC1 variants cause significantly more congenital glaucoma than do PITX2 variants, which are more associated with juvenile- and adult-onset glaucoma." (PMID 41011222, 2025). "FOXC1, a gene involved in ocular development, is associated with adult onset glaucoma in addition to congenital glaucoma." (PMID 36148008, 2022). "Of note, FOXC1 is required for proper development of the anterior segment and has been previously associated with congenital glaucoma." (PMID 34638643, 2021). "Gain-of-function RARB variants and increased FOXC1 gene dosage via gene duplication have both been associated with developmental ocular phenotypes similar to those observed in the individual presented here, including microphthalmia, anterior segment anomalies, and congenital glaucoma." (PMID 39450403, 2024). "The combination of aniridia with congenital glaucoma and aortic valvular disease would be consistent with previously reported FOXC1 deletions." (PMID 38050128, 2024). "Family history and the patient’s clinical presentation were suggestive of FOXC1-related anterior-segment-dysgenesis syndrome given the systemic findings, along with congenital glaucoma and normal foveal architecture." (PMID 36980998, 2023). "RA also directly regulates FOXC1 and PITX2, two transcription factors with fundamental roles in anterior segment development, likely explaining why ocular anomalies induced by FOXC1 and PITX2 mutations can phenocopy congenital glaucoma." (PMID 33975254, 2021). "A novel homozygous variant (c.92_100del; p.Ala31_Ala33del) in the FOXC1 gene segregated in a Pakistani family with ARS and congenital glaucoma." (PMID 27463523, 2016). "In addition, our study suggests that FOXC1 mutations, besides typical autosomal dominant ARS, can also cause ARS with congenital glaucoma through an autosomal recessive inheritance pattern." (PMID 27463523, 2016). "FOXC1 is a major transcription factor involved in the development of the anterior segment of the eye, which is involved in both anterior segment dysgenesis and congenital glaucoma phenotypes." (PMID 20485516, 2010). "No similar reports are available for FOXC1, but studies in mice demonstrated that Foxc1+/- heterozygotes as well as animals homozygous for mutations in congenital glaucoma genes Cyp1b1 and Angpt have abnormally formed trabecular meshwork and/or Schlemm’s canal." (PMID 36284357, 2022). "Forkhead box C1 (FOXC1), a member of the FOX protein family, is a key regulator of the development of the anterior chamber angle, and its abnormal expression correlates highly with the incidence of congenital glaucoma." (PMID 33987183, 2021). "Both the FOXC1 null (FOXC1−/−) and the heterozygous (FOXC1+/−) mice were found to have anterior segment abnormalities similar to those in humans with anterior segment dysgenesis (ASD) and congenital glaucoma." (PMID 21031026, 2010). "In the gene knockout groups with genes related to congenital glaucoma, GMDS, FOXC1, LTBP2, TEK, and CYP1B1, no distinct patterns were observed in the transcriptome of these gene knockout groups." (PMID 38272457, 2024).